ENSG00000285000 (novel protein, AGGF1-ZBED3-AS1 readthrough)
Gene: Protein-coding gene on chromosome 5 (77,030,902 to 77,152,155, forward strand). Ensembl gene ENSG00000285000.
Genetic constraint (gnomAD): Missense variants: 572 observed, 648.99 expected, observed/expected ratio (o/e) 0.88, 90% interval 0.82 to 0.94. Synonymous variants: 215 observed, 220.61 expected, observed/expected ratio (o/e) 0.97, 90% interval 0.87 to 1.09.